PIAS1 (protein inhibitor of activated STAT 1)
Description:
Functions as an E3-type small ubiquitin-like modifier (SUMO) ligase, stabilizing the interaction between UBE2I and the substrate, and as a SUMO-tethering factor. Catalyzes sumoylation of various proteins, such as CEBPB, MRE11, MTA1, PTK2, PML and ZNF76. In vitro, binds A/T-rich DNA. The effects of this transcriptional coregulation, transactivation or silencing, may vary depending upon the biological context. Mediates sumoylation of MRE11, stabilizing MRE11 on chromatin during end resection. Sumoylates PML (at 'Lys-65' and 'Lys-160') and PML-RAR and promotes their ubiquitin-mediated degradation (By similarity). PIAS1-mediated sumoylation of PML promotes its interaction with CSNK2A1/CK2 which in turn promotes PML phosphorylation and degradation (By similarity). Enhances the sumoylation of MTA1 and may participate in its paralog-selective sumoylation. Plays a dynamic role in adipogenesis by promoting the SUMOylation and degradation of CEBPB (By similarity). Mediates the nuclear mobility and localization of MSX1 to the nuclear periphery, whereby MSX1 is brought into the proximity of target myoblast differentiation factor genes (By similarity). Also required for the binding of MSX1 to the core enhancer region in target gene promoter regions, independent of its sumoylation activity (By similarity). Capable of binding to the core enhancer region TAAT box in the MYOD1 gene promoter (By similarity). (Microbial infection) Restricts Epstein-Barr virus (EBV) lytic replication by acting as an inhibitor for transcription factors involved in lytic gene expression. The virus can use apoptotic caspases to antagonize PIAS1-mediated restriction and express its lytic genes.
Synonyms: GBP; DDXBP1; GU/RH-II; ZMIZ3
Tractability: PROTAC: UniProt records ubiquitination sites on it; ubiquitination databases record sites on it; its protein half-life has been measured.
Gene: Protein-coding gene on chromosome 15 (68,054,301 to 68,198,603, forward strand). Ensembl gene ENSG00000033800.
Subcellular location: Nucleus; Nucleus speckle; Nucleus, PML body; Cytoplasm, cytoskeleton
Subcellular location (Human Protein Atlas): Nucleoplasm; Cytosol
Pathways (Reactome):
Metabolism of proteins: SUMOylation of DNA damage response and repair proteins; SUMOylation of chromatin organization proteins; SUMOylation of intracellular receptors; SUMOylation of transcription cofactors; SUMOylation of transcription factors; SUMOylation of ubiquitinylation proteins
DNA Repair: Formation of Incision Complex in GG-NER
Immune System: Regulation of IFNG signaling
Gene Ontology:
Molecular function: enzyme binding; protein binding; SUMO ligase activity; SUMO transferase activity; transcription regulator inhibitor activity; transcription cis-regulatory region binding; transcription coregulator activity; transcription corepressor activity; DNA-binding transcription factor binding; protein domain specific binding; ubiquitin protein ligase binding; zinc ion binding
Biological process: DNA damage response; negative regulation of receptor signaling pathway via JAK-STAT; positive regulation of protein sumoylation; positive regulation of transcription by RNA polymerase II; positive regulation of transcription initiation by RNA polymerase II; protein sumoylation; cell surface receptor signaling pathway via JAK-STAT; negative regulation of transcription by RNA polymerase II; positive regulation of proteasomal ubiquitin-dependent protein catabolic process; regulation of cell population proliferation; fat cell differentiation; G1/S transition of mitotic cell cycle; negative regulation of apoptotic process; positive regulation of DNA-templated transcription; positive regulation of protein localization to cell periphery; positive regulation of smooth muscle cell differentiation; protein-DNA complex assembly; spermatogenesis; visual learning
Cellular component: nucleus; chromatin; nuclear periphery; nucleoplasm; PML body; cytoskeleton; glutamatergic synapse; nuclear speck; postsynaptic cytosol; presynaptic cytosol
Genetic constraint (gnomAD): Loss-of-function variants: 1 observed, 34.46 expected, observed/expected ratio (o/e) 0.029, 90% interval 0.009 to 0.14. The upper end of that interval is the gene's LOEUF score, 0.14, which puts it in group 1 of 6, group 1 being the genes least tolerant of losing a copy. Missense variants: 414 observed, 569.81 expected, observed/expected ratio (o/e) 0.73, 90% interval 0.67 to 0.79. Synonymous variants: 222 observed, 217.48 expected, observed/expected ratio (o/e) 1.02, 90% interval 0.91 to 1.14.
Homologues: Orthologues: macaque PIAS1 (100% identical), dog PIAS1 (99% identical), pig PIAS1 (99% identical), chimpanzee PIAS1 (99% identical), guinea pig PIAS1 (98% identical), rat Pias1 (98% identical), mouse Pias1 (98% identical), rabbit PIAS1 (98% identical), tropical clawed frog pias1 (86% identical), zebrafish pias1b (78% identical), zebrafish pias1a (77% identical), Drosophila melanogaster Su(var)2-10 (37% identical). Paralogues in human: PIAS3 (58% identical), PIAS2 (56% identical), PIAS4 (37% identical), ZMIZ2 (23% identical), ZMIZ1 (22% identical).
Diseases named in the same sentence as PIAS1 in open-access papers:
PIAS1 is named in the same sentence as 71 diseases in open-access papers, as found by Europe PMC text mining. Sharing a sentence is not in itself a finding about the gene and the disease. The quoted sentences say what the papers report.
breast carcinoma (21 papers, 2014 to 2025). "It is also noteworthy that some RUNX1 mutants associated with breast cancer cannot be sumoylated through PIAS1, and that in sumoylation defective mutants of RUNX3 the tumor suppressor capacity is nullified, promoting tumor growth." (PMID 35887358, 2022). "Elevated expression of protein inhibitor of activated STAT 1 (PIAS1) is found in breast cancer tissues and it has been shown to associate with methylated regions of WNT-5A promoter in breast cancer cells." (PMID 26514730, 2016). "Interestingly, the upregulation of PIAS1 is associated with epigenetic silencing of breast cancer-associated genes, including ESR1 (ERα)." (PMID 34503213, 2021). "The prognostic value of PIAS1 revealed the detailed mechanism of the protein in SnoN SUMOylation, which supports great opportunity for breast cancer therapy." (PMID 38590645, 2024). "In contrast, PIAS1 acted as a protective role in breast cancer (DFS, RFS), Head and neck cancer (RFS), and Lung cancer (RFS)." (PMID 38528630, 2024). "SUMO1/2 and PIAS1 have been reported to promote SUMOylation of vimentin, which plays an important role in enhancing breast cancer metastasis." (PMID 37833712, 2023). "Dadakhujaev and co-workers reported that the SUMO E3 ligase PIAS1 suppresses TGF-β-induced activation of the matrix metalloproteinase MMP2 in human breast cancer cells." (PMID 35408996, 2022). "Some reports have shown that PIAS1 is highly expressed in breast cancer and regulates breast cancer tumorigenesis." (PMID 33968766, 2021). "In triple-negative breast cancer (TNBC), PIAS1 promotes the SUMOylation of SnoN that suppresses TGFβ-induced EMT in TNBC MDA-MB-231 cell-derived organoids similarly to HR-positive breast cancer models." (PMID 34503213, 2021). "Consistently, PIAS1 acts in a SUMO-E3 ligase-dependent manner to suppress the rate of breast-cancer cell-derived metastatic growth in a xenograft model." (PMID 30096838, 2018). "Data also suggest that the PIAS1-SnoN SUMOylation axis suppresses TGFβ-induced invasive growth of 3D-breast cancer cell-derived organoid system." (PMID 30096838, 2018). "In this study, we identify PIAS1 as a biomarker that predicts disease-specific overall survival (DSOS) in endocrine-treated breast cancer patients." (PMID 28493978, 2017). "Conversely, coexpression of SnoN (KdR) antagonized the ability of overexpressed PIAS1 to suppress TGFβ-induced invasive growth of three-dimensional breast cancer cell-derived organoids." (PMID 28493978, 2017). "Our studies thus identify the SUMO E3 ligase PIAS1 as a prognostic biomarker in breast cancer, and suggest a potential role for the PIAS1-SnoN sumoylation pathway in controlling breast cancer metastasis." (PMID 28493978, 2017). "The SUMO E3 ligase PIAS1 inhibits the invasive behaviour of breast cancer cells grown in a three-dimensional model system, and deregulation of PIAS1 activity promotes the growth of breast cancer cell-derived metastases in a xenograft mouse model." (PMID 28493978, 2017). "The related protein PIAS1 acts in a SUMO E3 ligase-dependent manner to suppress EMT in mammary epithelial cells as well as the invasive growth or metastatic growth of breast cancer cells in three-dimensional cultures and xenograft model." (PMID 28423498, 2017). "In mechanistic studies, we have found that PIAS1 suppresses the invasive behaviour of human breast cancer cell-derived organoids via sumoylation of the transcriptional regulator SnoN." (PMID 28493978, 2017). "The identification of PIAS1 abundance and nuclear localization as potential useful biomarkers in prognosis of breast cancer is significant, in view of the scarcity of useful biomarkers in this disease." (PMID 28493978, 2017). "The potential utility of PIAS1 as a biomarker in predicting breast cancer patient survival is buttressed by new insights into the role of PIAS1 in breast cancer pathogenesis." (PMID 28493978, 2017).
breast carcinoma (continued). "Growing evidence has implicated the SUMO E3 ligase PIAS1 in the regulation of EMT in mammary epithelial cells and breast cancer metastasis." (PMID 28493978, 2017). "In mechanistic studies, we find that PIAS1 acts via sumoylation of SnoN to suppress the invasive growth of human breast cancer cell-derived organoids." (PMID 28493978, 2017). "Recent evidence suggests that PIAS1 suppresses the invasive and metastatic growth of human breast cancer cells in three-dimensional-derived multicellular structures and xenograft animal model, respectively." (PMID 28493978, 2017). "In mechanistic studies, we find that PIAS1 acts via sumoylation of the transcriptional regulator SnoN to suppress invasive growth of MDA-MB-231 human breast cancer cell-derived organoids." (PMID 28493978, 2017). "PIAS1 triggers sumoylation of the transcriptional regulator SnoN, which mediates the ability of PIAS1 to suppress the invasive growth of three-dimensional breast cancer cell-derived organoids." (PMID 28493978, 2017). "Our study advances our understanding of the mechanisms by which PIAS1 suppresses the invasive behaviour of breast cancer cell-derived organoids." (PMID 28493978, 2017). "In this study, we have identified the SUMO E3 ligase PIAS1 as a biologically relevant biomarker in breast cancer that predicts patient survival." (PMID 28493978, 2017). "In conclusion, we have demonstrated the prognostic value of PIAS1 in breast cancer and elucidated a mechanism for its potential action in the malignant behaviour of breast cancer." (PMID 28493978, 2017). "Our findings suggest that nuclear localization of PIAS1 predicts improved breast cancer patient survival." (PMID 28493978, 2017). "Using tissue-microarray analysis (TMA), we report that the protein abundance and subcellular localization of PIAS1 correlate with disease specific overall survival of a cohort of breast cancer patients." (PMID 28493978, 2017). "Studies on screening for drugs that stabilize PIAS1 in breast cancer should be performed to determine effect on cancer cell invasion and metastasis." (PMID 28493978, 2017). "We used tissue microarray (TMA) analysis to assess the protein abundance and localization of PIAS1 in human breast cancer." (PMID 28493978, 2017). "We have found that the abundance of PIAS1 and its nuclear localization correlate positively with disease specific overall survival of breast cancer patients." (PMID 28493978, 2017). "In summary, our findings have revealed an important role for PIAS1 as a predictive biomarker for breast cancer patient outcome." (PMID 28493978, 2017). "Using AQUA analyses, we found that patients with any detectable amount of PIAS1 were less likely to have a DSOS event (death due to breast cancer) [HR = 0.38, 95% confidence interval (CI): 0.17–0.84, p = 0.016]." (PMID 28493978, 2017). "Together, these findings suggest that the protein abundance and nuclear localization of PIAS1 predict improved survival in breast cancer patients." (PMID 28493978, 2017). "Collectively, these data support the idea that PIAS1 acts via sumoylation of SnoN to suppress the invasive growth of breast cancer cells." (PMID 28493978, 2017). "It leads to reduction in the number of tumor-initiating cells and attenuates breast cancer growth in vivo suggesting that epigenetic silencing of WNT-5A via PIAS1 is an important feature in breast cancer." (PMID 26514730, 2016). "Collectively, our findings define a novel function for the SUMO E3 ligase PIAS1 in the regulation of breast cancer invasiveness and metastasis." (PMID 25594015, 2014). "We also find that knockdown of endogenous PIAS1 or inhibition of its SUMO E3 ligase activity stimulates the ability of TGFβ to induce an aggressive phenotype in three-dimensional breast cancer cell organoids." (PMID 25594015, 2014). "We next determined the function of PIAS1 in TGFβ-regulation of MDA-MB-231 breast cancer cell-derived organoids." (PMID 25594015, 2014).
breast carcinoma (continued). "In future studies, it will be important to determine how PIAS1 suppresses the growth of breast cancer cell-derived skeletal metastases, a process that shows some dependency on latent TGFβ released from bone as a result of osteoclastic activity." (PMID 25594015, 2014). "Remarkably, PIAS1 also acts in a SUMO E3 ligase-dependent manner to suppress the ability of breast cancer cells to metastasize to bone in a murine xenograft model." (PMID 25594015, 2014). "IHC analyses indicate that PIAS1 is significantly upregulated in primary breast cancer samples at early stages of breast ductal carcinoma in situ (DCIS) as well as invasive ductal carcinoma (IDC)." (PMID 24586797, 2014). "Collectively, our findings define a novel and critical role for the SUMO E3 ligase PIAS1 in the regulation of the invasive and metastatic potential of malignant breast cancer cells." (PMID 25594015, 2014). "Collectively, our findings define a critical role for the interplay of PIAS1 and TGFβ signaling in the regulation of breast cancer metastasis." (PMID 25594015, 2014). "The PIAS1 (CS) mutant acts in a dominant negative manner to inhibit endogenous PIAS1-regulation of MDA-MB-231 breast cancer cell invasiveness in standard and three-dimensional cultures." (PMID 25594015, 2014). "Here, we report that expression of the SUMO E3 ligase PIAS1 suppresses TGFβ-induced activation of the matrix metalloproteinase MMP2 in human breast cancer cells." (PMID 25594015, 2014). "In conclusion, we have uncovered the SUMO E3 ligase PIAS1 as a novel regulator of breast cancer invasion and metastasis." (PMID 25594015, 2014). "We assessed the effect of expression of PIAS1 on the ability of TGFβ to augment MMP activation in MDA-MB-231 breast cancer cells." (PMID 25594015, 2014). "In this study, we have discovered that the SUMO E3 ligase PIAS1 is a critical regulator of breast cancer invasion and metastasis." (PMID 25594015, 2014). "The three-dimensional organoid model system used in this study facilitated the identification of the SUMO E3 ligase PIAS1 as a regulator of breast cancer invasion and metastasis." (PMID 25594015, 2014). "Western blot analysis revealed that PIAS1 became phosphorylated on Ser90 in response to EGF or Heregulin in various breast cancer cell lines, including MDA-MB231, BT-20, BT-474 and HCC-1954." (PMID 24586797, 2014). "PIAS1 knockdown in breast cancer cells reduced the subpopulation of tumor-initiating cells, and inhibited breast tumor growth in vivo." (PMID 24586797, 2014). "The finding that PIAS1 inhibits breast cancer invasion and metastasis bears significant implications for our understanding of the biology of epithelial tumors." (PMID 25594015, 2014). "Consistently, loss and gain of function studies demonstrate that PIAS1 acts in a SUMO E3 ligase-dependent manner to counteract the ability of TGFβ to induce the invasive and aggressive phenotypes of breast cancer cell-derived organoids." (PMID 25594015, 2014). "Conversely, PIAS1 suppresses TGF-β-driven EMT in breast cancer via SUMOylation of SnoN." (PMID 40941002, 2025). "PIAS1-mediated AIBI SUMOylation needs to be further investigated for breast cancer therapy." (PMID 38590645, 2024). "Foregoing investigation has revealed PIAS1 as a biomarker for breast cancer patients." (PMID 38590645, 2024). "Inhibition of PIAS1 in breast cancer cells promotes metastases in mice in vivo." (PMID 35408996, 2022). "However, PIAS1 is essential for viability of MYC-dependent breast cancer cells, as the silencing of PIAS1 reduces the proliferation of MYC-dependent MDA-MB-231 cells, but not MYC-independent MCF7 cells." (PMID 34503213, 2021). "PIAS1 SUMOylation regulates the invasive and metastatic potential of malignant breast cancer cells." (PMID 33968766, 2021). "The role of PIAS1 in breast cancer may be a double-edged sword, and further investigations are required to clarify its regulatory mechanism." (PMID 33968766, 2021).